ENSG00000188223 (novel protein)
Gene: Protein-coding gene on chromosome 19 (35,745,678 to 35,754,519, forward strand). Ensembl gene ENSG00000188223.
Genetic constraint (gnomAD): Missense variants: 60 observed, 63.4 expected, observed/expected ratio (o/e) 0.95, 90% interval 0.77 to 1.17. Synonymous variants: 21 observed, 25.78 expected, observed/expected ratio (o/e) 0.81, 90% interval 0.58 to 1.17.